KNG1 (kininogen 1)
Diseases named in the same sentence as KNG1 in open-access papers (continued):
Sharing a sentence is not in itself a finding about the gene and the disease.
cancer (43 papers, 2009 to 2026). A tumor composed of atypical neoplastic, often pleomorphic cells that invade other tissues. "For example, KNG1 was mutated in 690 patients across 25 cancer types, accounting for 6% of the 10,803 patients." (PMID 35052689, 2021). "The L_cancer patient prognosis features and risk score were calculated as: KNG1 × 0.621 + CYP11A1 × 0.600 + SMPD1 × 1.370 + DAND5 × 0.859 + NKPD1 × 0.721 + RP11-59D5_B.2 × 0.568 + CTD-2184C24.2 × 0.514 + RP11-680F8.3 × 0.517 − RP11-51F16.9 × 0.731 + CTD-2012K14.8 × 0.765." (PMID 36419007, 2022). "KNG1 is an inhibitor of cysteine proteins known to inhibit cell proliferation and angiogenesis and demonstrate a role in cancer development." (PMID 38902713, 2024). "Kininogen 1 (KNG1) is a crucial component of the blood coagulation system whose expression is lowered in a variety of cancers including breast, ovarian, and prostate." (PMID 37719007, 2023). "As a precursor protein of vasoactive kinin, KNG1 is closely correlated with the progression of many diseases and cancers." (PMID 36550594, 2023). "A low expression of KNG1 in tumors inhibits the occurrence and development of cancer and inhibits apoptosis." (PMID 35935258, 2022). "The low expression of KNG1 in cancer patients increases the vitality of cancer cells and plays a crucial role in carcinogenesis." (PMID 35935258, 2022). "Recently, KNG1 has been demonstrated to exert an effect on carcinogenesis and its low expression in plasma of the cancer patients is revealed to promote the viability of the cancer cells." (PMID 30068373, 2018). "Moreover, the change in the expression of TUBA1C, PRDX4, LDHC, C7, and KNG1 due to NVA-AA treatment corroborated with the sensitivity provided by CTRP drugs to cancer cells." (PMID 37719007, 2023). "It should also be noted that TTR and KNG1 were also expressed and suppressed in other types of cancer, while AHSG and F2 were only expressed in CCA and liver hepatocellular carcinoma and only suppressed in CCA, which indicates that AHSG and F2 have higher specificity." (PMID 36224755, 2022). "Kininogen-1 has recently been investigated as a biomarker in cancer and mental diseases." (PMID 34836106, 2021). "KNG1 plays a crucial role in carcinogenesis.Low levels of KNG1 in blood samples from cancer patients may be propitious to the viability of the cancer cells." (PMID 30068373, 2018). "Although its mechanistic role remains unclear in cancer, KNG1 could have antiangiogenic properties and inhibitory actions on proliferation of endothelial cells." (PMID 28344541, 2017). "Since kininogen-1 is known for its antiangiogenic properties and inhibitory action on the proliferation of endothelial cells, its lowered expression in serum/plasma of the cancer patients was believed to have contributed to the survival of the cancer cells." (PMID 21083881, 2010). "Hence detection of KNG1 as a whole or specifically its light chain could be futher investigated as promising targets for cancer diagnosis." (PMID 28344541, 2017). "Furthermore, in cancer patients, lower levels of kininogen-1 expression have been detected in blood samples, and these levels may contribute to the survival of the cancer cells present." (PMID 23894665, 2013). "CALM1/CALM2/CALM3, the latent IPF-features are the known downstream targets of KNG1 (ligand)—BDKRB1 (receptor) signaling (KEGG: hsa05200, Pathways in cancer)." (PMID 38081956, 2023). "In KEGG pathway analysis, KNG1 was dramatically enriched in PI3K/AKT signaling pathway, cell circle, damage vessel and pathways in cancer." (PMID 30068373, 2018). "However, no research has shown that KNG1, FBN1, MATN3, and SERPINC1 play an important role in cancer chemotherapy resistance." (PMID 34737677, 2021).
tumor (33 papers, 2009 to 2026). "Previous studies have demonstrated that the core genes of NPC-RSS, including SMARCA2, DMC1, CD9, PSG4, and KNG1, are associated with tumor radiosensitization to varying degrees." (PMID 40530955, 2025). "Given the AUC value, salivary MLT could present a satisfactory diagnostic tool for OSCC as a tumour biomarker alone or in along with some other molecules, such as kininogen 1, cathepsin V, kallikrein 5 or matrix metalloproteinase 146–48." (PMID 34168230, 2021). "Further analysis of receptor-ligand interactions highlighted the roles of KNG1_BDKRB2 and NRG1_ERBB4 signaling in promoting tumor aggression, suggesting potential therapeutic targets." (PMID 40969325, 2025). "Kininogen 1 secretion into urine was found to be lower in patients with RCC tumor in comparison to the control group." (PMID 34572331, 2021). "Furthermore, overexpression of KNG1 decreased the tumor growth and promoted the apoptosis of decreased by overexpression of KNG1 in vivo." (PMID 30068373, 2018). "Moreover, the VEGF expression were decreased by the overexpression of KNG1, contributing to the reduction of tumor angiogenesis." (PMID 30068373, 2018). "Moreover, the level of KNG1 was also enhanced in the tumor tissues of mice injected with SHG-44 cells and the expressions of XIAP and VEGF were inhibited (P < 0.05)." (PMID 30068373, 2018). "Moreover, the tumor weight and tumor volume were obviously decreased in the mice injected with U87-MG cells overexpressing KNG1 (P < 0.05)." (PMID 30068373, 2018). "Their hypothesis to explain this observation was that an increased production of KNG1 derives from tumor tissues." (PMID 28344541, 2017). "Although it remains unclear why this was observed, it is hypothesized that increased production of kininogen-1 derives from tumor tissues." (PMID 23894665, 2013). "This suggests that KNG1_BDKRB2 may be involved in tumor progression." (PMID 40969325, 2025). "Therefore, detection of kininogen-1 in combination with other tumor markers is recommended." (PMID 23894665, 2013). "Over-expression of KNG1 can inhibit the activity of PI3K/Akt, decrease tumor growth, and promote apoptosis." (PMID 36419007, 2022). "Since C1QBP and KNG1 are supposed to be involved in the crosstalk between KLK11 and CCDC25, their role in tumor metastasis should be explored." (PMID 34067437, 2021). "The expressions of KNG1, XIAP and VEGF were detected in the tumor tissues of mice injected with U87-MG cells." (PMID 30068373, 2018). "In conclusion, suppression of DAPK1 may accelerate tumor growth and result in the upregulation of C3, TIMP-1, and AHSG expression and downregulation of KNG1 expression." (PMID 35935258, 2022). "For several proteins, like ALB and KNG1, the discordance between low gene expression levels in CCA tumor tissue and increased peptide levels may be explained in part by increased expression of these proteins in tissue adjacent to the tumor." (PMID 31900160, 2020).
infection (11 papers, 2011 to 2025). The state of being infected such as from the introduction of a foreign agent such as serum, vaccine, antigenic substance or organism. "By contrast, the pool of genes induced during ΔF2 Nig06 infection is mainly involved in the mounting of an immune response: Trem1, Kng1, Nfatc2ip and Xcr1 are particularly implicated in mediation of inflammation, cytokine induction and leukocyte chemoattraction." (PMID 23469251, 2013). "Increase in genes associated with intrinsic and common coagulation pathways, namely KNG1 and FGA, are upregulated early in both HTNV and ANDV infection (6 hpi to 2 dpi) and peak expression occurs coinciding with ANDV viremia (FGA >11 log2 fold on 10 and 12 dpi, KNG1 >4 log2 fold on 10 and 12 dpi)." (PMID 34339406, 2021).
cardiovascular disease (5 papers, 2021 to 2024). "As is previously known from the literature, high levels of KNG1 and low amounts of A1AT are related to an increased risk for cardiovascular disease." (PMID 37034443, 2023).
kidney disease (3 papers, 2022 to 2025). "Having established the platform-specific influence of APOL1, KLKB1, F12, and KNG1 variants on Olink and SomaLogic measurements of plasma APOL1, we investigated whether these variants may also be relevant to APOL1-associated pathologies, specifically kidney disease." (PMID 39975113, 2025).
myopathy (1 paper, 2015). A disease of the muscle in which the muscle fibers do not function properly. "Birds suffering from this myopathy exhibit down-regulation of eight hemostatic genes (A2M, FGA, FGB, FGG, KNG1, SERPINC1 and VWF) and up-regulation of four other coagulation genes (F5, F10, PROS1 and F2R)." (PMID 26445145, 2015).
KNG1 also shares sentences with these, for which no sentence is quoted: ischemia (7 papers); endothelial dysfunction (6); Alzheimer disease (5); neurodegenerative disease (5); colorectal adenoma (4); anaphylaxis (3); Ataxia (3); brain ischemia (3); cerebral infarction (3); edema (3); interstitial cystitis (3); lung carcinoma (3); oral cancer (3); pulmonary edema (3); Candida infection (2); chronic pancreatitis (2); coronary heart disease (2); infectious disease (2); inflammatory bowel disease (2); malaria (2); melanoma (2); osteoarthritis (2); vascular disorder (2); venous thromboembolism (2); acute pancreatitis (1); acute respiratory distress syndrome (1); age-related macular degeneration (1); AIDS (1); airway hyperresponsiveness (1); Airway obstruction (1).
A further 86 diseases each share a sentence with KNG1 in 1 paper.